RBM5 (RNA binding motif protein 5)
Diseases named in the same sentence as RBM5 in open-access papers (continued):
Sharing a sentence is not in itself a finding about the gene and the disease.
Huntington disease (3 papers, 2023 to 2024). Huntington disease (HD) is a rare neurodegenerative disorder of the central nervous system characterized by unwanted choreatic movements, behavioral and psychiatric disturbances and dementia. "More recent studies revealed that RBM5 is critical in neuronal injury response and participates in mouse models of Huntington’s disease." (PMID 38216972, 2024). "Analysing brain tissue from males of the Huntington’s disease (HD) R6/2 mouse model uncovered differential RNA-binding of the alternative splicing regulator RBM5." (PMID 37468457, 2023). "Here, the authors describe the Brain-pCLAP methodology, uncover the RBP atlas of the mouse brain and demonstrate the differential binding of the splicing factor RBM5 to Huntington’s disease relevant transcripts in R6/2 mice." (PMID 37468457, 2023). "Interestingly, a significant number (40%) of the identified RBM5 interactors also constitute known HTT interactors 79,80, with the shared interactors between RBM5 and HTT highly enriched for proteins involved in mRNA metabolic processes, neuron specific processes and Huntington’s disease." (PMID 37468457, 2023).
pancreatic cancer (3 papers, 2013 to 2017). "Underexpression of RBM5 in pancreatic cancers was found to be significantly associated with lymph node metastasis, distant metastasis, Union for International Cancer Control (UICC) stage and nerve and venous invasion (P<0.05)." (PMID 23425895, 2013). "The differentially expressed RBM5 and KRAS in pancreatic cancer and their significant associations with postoperative recurrence of pancreatic cancer suggests their potential use as predictors of clinical implication." (PMID 23425895, 2013). "Further research is required to determine the role of RBM5 in metastasis and invasion of pancreatic cancer." (PMID 23425895, 2013). "Taken together, it is clear that the role of RBM5 in pancreatic cancer is still not fully understood." (PMID 23425895, 2013). "Analysis revealed that RBM5 expression was negatively correlated with KRAS expression in pancreatic cancer." (PMID 23425895, 2013). "There is a close association of differential RBM5 and KRAS with poor clinicopathological features, suggesting their potential roles in the progression and metastasis of pancreatic cancer." (PMID 23425895, 2013). "In the present study, significantly reduced RBM5 expression was observed in pancreatic cancer tissues compared to peritumoral tissues." (PMID 23425895, 2013). "The expression of RBM5 was significantly downregulated in pancreatic cancer tissues compared to peritumoral tissues at the mRNA and protein levels." (PMID 23425895, 2013). "Compared to the peritumoral tissues, RBM5 was downregulated in pancreatic cancers (P<0.05)." (PMID 23425895, 2013). "Additionally, underexpression of RBM5 and overexpression of KRAS in pancreatic cancer has a close association with metastasis and invasion-related clinicopathological features, suggesting their collaboration in prompting tumor ability of invasion and metastasis." (PMID 23425895, 2013). "Our results revealed that the expression of RBM5 and KRAS is negatively correlated in pancreatic cancer." (PMID 23425895, 2013). "Significant RBM5 underexpression and KRAS overexpression were observed in pancreatic cancer compared to non-tumor tissues." (PMID 23425895, 2013). "Detection of RBM5 and KRAS expression by quantitative reverse transcription-polymerase chain reaction (qRT-PCR) and western blotting was performed at mRNA and protein levels, respectively, in pancreatic cancer and non-tumor tissues." (PMID 23425895, 2013).
schwannoma (3 papers, 2012). A benign, usually encapsulated slow growing tumor composed of Schwann cells. "RBM5 mRNA was downregulated in spontaneously developing human tumors such as human schwannomas as well as in transformed cells, such as ras-transformed Rat-1 rat embryonic fibroblastic cells." (PMID 23158838, 2012). "Moreover, RBM5 mRNA was downregulated in spontaneously developing human tumors such as human schwannomas and in transformed cells, such as ras-transformed Rat-1 rat embryonic fibroblastic cells." (PMID 22866867, 2012).
acute myeloid leukemia (2 papers, 2024 to 2025). Acute myeloid leukemia (AML) is a group of neoplasms arising from precursor cells committed to the myeloid cell-line differentiation. "Such mutations, including hotspots in SF3B1 and U2AF1 and loss-of-function events in FUBP1, RBM5, RBM10, and ZRSR2, are recurrent in myelodysplastic syndromes, acute myeloid leukemia, chronic myelomonocytic leukemia, and multiple solid tumors 8,42–45." (PMID 41279721, 2025). "Although we have confirmed that RBM5 is required for the survival of acute myeloid leukemia cells, it is equally important to reveal the downstream regulation mechanism of RBM5." (PMID 38216972, 2024). "RBM5 is highly overexpressed in acute myeloid leukemia (AML) patients compared to healthy individuals." (PMID 38216972, 2024). "Overall, we find that RBM5 is a new regulator in HOXA9 regulation and controls acute myeloid leukemia development." (PMID 38216972, 2024). "Here, using HOXA9-reporter-based genome-wide CRISPR/Cas9 screens, we identified that RBM5 is a positive regulator for maintaining HOXA9 expression and acute myeloid leukemia survival." (PMID 38216972, 2024).
breast tumor (2 papers, 2007 to 2013). "In breast tumour tissue, chimeric expression was associated with elevated levels of RBM6 and RBM5 mRNA, and increased tumour size." (PMID 17908320, 2007). "Expression of RBM5 mRNA is downregulated in tumour tissue compared to normal tissue, although our recent study reports that expression of RBM5 mRNA is marginally upregulated (p = 0.063) and protein is significantly upregulated (p = 1.43 × 10-8) in breast tumour tissue." (PMID 17908320, 2007).
large cell carcinoma (2 papers, 2012 to 2013). A malignant epithelial neoplasm composed of large, atypical cells. "The one tumor sample with no change in RBM5 mRNA expression compared to its non-tumor tissue was an adenocarcinoma, while the one tumor sample that had more RBM5 mRNA than its non-tumor tissue was a large cell carcinoma." (PMID 22866867, 2012).
lymph node metastasis (2 papers, 2012 to 2013). "The reduced expression of RBM5 protein was associated with tobacco smoke, tumor stages, and lymph node metastasis of NSCLC, while overexpression of EGFR and KRAS proteins was associated with tumor stages and lymph node metastasis of NSCLC." (PMID 22537942, 2012). "Additionally, underexpression of RBM5 had a close association with unfavorable clinicopathological features, including lymph node metastasis, distant metastasis, advanced UICC stage and presence of nerve and venous invasion, suggesting its potential role in tumor invasion and progression." (PMID 23425895, 2013). "Reduced RBM5 protein expression in the NSCLC tissues was also significantly positively correlated with lymph node metastasis of NSCLC patients (50 vs. 34 or 83 % vs. 56.7 %; P = 0.008)." (PMID 22537942, 2012). "In contrast to RBM5, overexpression of KRAS was significantly correlated with tumor size, lymph node metastasis, UICC stage and nerve invasion (P<0.05)." (PMID 23425895, 2013).
medulloblastoma (2 papers, 2021 to 2022). A malignant, invasive embryonal neoplasm arising from the cerebellum. "Compared with normal tissues, RBM5 was significantly lower in medulloblastoma and RBM5 overexpression repressed cell proliferation and migration in vitro." (PMID 36193508, 2022). "RBM5 inhibited cell proliferation and migration of medulloblastoma." (PMID 34804951, 2021).
cardiac arrest (1 paper, 2020). Cessation of breathing and/or cardiac function. "RBM5 KO mice also need to be studied in pre-clinical models of CNS injury besides trauma (e.g., stroke, cardiac arrest, and neurodegenerative diseases)." (PMID 32765218, 2020).
chordoma (1 paper, 2011). Chordomas are rare malignant tumors arising from embryonic remnants of the notochord in axial skeleton. "This region contains multiple genes, including RBM5, FHIT and PTPRG, but their involvement in chordoma pathogenesis has yet to be determined." (PMID 22613809, 2011).
cognitive deficits (1 paper, 2023). "RBM5, PNISR (also known as SFRS18) and HNRNPM code for RNA-binding proteins, and dysregulations of these genes are associated with carcinogenesis, psoriasis and cognitive deficits, respectively." (PMID 37026480, 2023).
colon cancer (1 paper, 2020). "The RBM5 anti-sense transcript (lncRNA RBM5-AS1) sustains the function of colon cancer-initiating cells through the organization of a transcriptional complex containing β-catenin and transcription factor 4 (TCF4)." (PMID 32429086, 2020).
coronary artery disease (1 paper, 2023). "A GWAS on 188,578 individuals found that a small nucleotide polymorphism in an RBM5 gene intron (rs2013208; MAF = 0.5) is associated with high HDL levels and coronary artery disease." (PMID 37848418, 2023).
endometrial cancer (1 paper, 2024). Primary or metastatic malignant neoplasm involving the endometrium (mucous membrane that lines the endometrial cavity). "ZNF554 inhibits the progression of endometrial cancer by regulating RBM5 and inactivating WNT/β-Catenin signaling pathway." (PMID 39717098, 2024).
lentivirus infection (1 paper, 2017). Virus diseases caused by the Lentivirus genus. "Both mRNA and protein level of RBM5 was successfully upregulated in U251 and SHG44 cells compared to the parent cells after lentivirus infection for 96 h." (PMID 28061901, 2017).
leukemia (1 paper, 2024). A malignant (clonal) hematologic disorder, involving hematopoietic stem cells and characterized by the presence of primitive or atypical myeloid or lymphoid cells in the bone marrow and the blood. "We observed that RBM5 is essential in multiple leukemia cell lines, including both KMT2A-r and non-KMT2A-r-mutated cell lines, from the public DepMap dataset." (PMID 38216972, 2024). "Ectopic expression of HOXA9 rescues impaired leukemia cell proliferation upon RBM5 loss." (PMID 38216972, 2024). "RBM5 loss triggered by CRISPR knockout and shRNA knockdown significantly impairs leukemia maintenance in vitro and in vivo." (PMID 38216972, 2024). "From our screen, most of the sgRNAs targeting RBM5 are significantly enriched in the HOXA9Low population, suggesting an oncoprotein function in leukemia." (PMID 38216972, 2024). "More importantly, the overexpression of FLT3 significantly restored the cell expansion in the RBM5 sgRNA-treated leukemia cells, similar to the extent of both RBM5 and HOXA9 overexpression." (PMID 38216972, 2024). "The integrative analysis further suggested that the HOXA9/FLT3 axis promises the dominant downstream target of RBM5, as demonstrated by functional rescue assay and transcriptional regulation in leukemia cells." (PMID 38216972, 2024). "Here, we demonstrated that both the RNA- and DNA-binding domains are essential for leukemia cell growth, suggesting that RBM5 functions as both RNA splicing and transcription regulation." (PMID 38216972, 2024). "To test this, we performed an anti-MYC tag antibody ChIP (chromatin immunoprecipitation) to analyze the chromatin occupancy of exogenous RBM5-MYC expressed in OCIAML2 leukemia cells." (PMID 38216972, 2024). "Strikingly, RBM5 shRNA-treated animals exhibited much less splenomegaly and reduced leukemia cell infiltration in bone marrow, spleen, and peripheral blood compared to the wild-type control." (PMID 38216972, 2024). "Overall, our data support that RBM5 maintains leukemia cell survival in both cell lines and primary samples while not required for normal human myeloid proliferation and differentiation." (PMID 38216972, 2024). "We identify a poorly characterized RNA-binding protein, RBM5, as the top candidate gene required to maintain leukemia cell fitness." (PMID 38216972, 2024). "This is consistent with our evidence that HOXA9 could restore the FLT3 expression in RBM5 null leukemia cells." (PMID 38216972, 2024). "Notably, the overexpression of HOXA9 significantly restored the cell expansion in the RBM5 sgRNA-treated leukemia cells, similar to the extent of RBM5 overexpression." (PMID 38216972, 2024). "RBM5 was shown to be the highest expression level in leukemia across all cancer types." (PMID 38216972, 2024). "Therefore, we utilized the auxin-induced degron (AID) system and generated two endogenous RBM5 N-terminus AID knock-in KMT2A-r leukemia lines (SEM homozygous clones and MOLM13 bulk cells)." (PMID 38216972, 2024). "Moreover, we constructed RBM5 cDNA mutants by truncating six individual known domains and further confirmed the functional role of different domains of RBM5 in leukemia cell growth." (PMID 38216972, 2024). "Furthermore, we showed that both the RNA-binding and DNA-binding domains are required for RBM5’s role in leukemia." (PMID 38216972, 2024). "More importantly, although RBM5 controls thousands of splicing events in leukemia cells, the differential genes after RBM5 loss were not due to the splicing defects." (PMID 38216972, 2024). "Because overexpression of HOXA9 rescued the defects of leukemia growth after RBM5 loss, we speculate that the noncanonical transcriptional regulation of HOXA9 by RBM5 is one of the primary mechanisms in AML." (PMID 38216972, 2024). "However, the remaining question in the study is whether RBM5 interacts with other key transcriptional factors for gene transcription in leukemia." (PMID 38216972, 2024).
leukemia (continued). "To comprehensively understand the downstream target genes of RBM5 in AML, we performed genome-wide transcriptome analysis by RNA-seq in the leukemia cell line MOLM13 with both RBM5 knockout (RBM5 KO) and RBM5 overexpression (RBM5 OE) compared to wild-type controls." (PMID 38216972, 2024). "To further explore the underlying molecular mechanism, we performed transcriptome analysis with and without HOXA9 overexpression (HOXA9 OE) in the RBM5 knockout leukemia cells." (PMID 38216972, 2024). "Of note, we observed that the growth defect of RBM5 knockout cells could be fully rescued by the exogenous expression of sgRNA-resistant RBM5 cDNA but not the wild type in all three leukemia cell lines (MOLM13, THP1, and OCIAML2)." (PMID 38216972, 2024).
male infertility (1 paper, 2022). The inability of the male to effect fertilization of an ovum after a specified period of unprotected intercourse. "One gene we identify, RBM5, is an essential regulator of male germ cell pre-mRNA splicing and has been previously implicated in male infertility in mice." (PMID 35013161, 2022). "We identify a number of promising candidate genes for male infertility, including the mRNA splicing gene RBM5, which contains a possibly causative DNM in our trio cohort, and possibly causative heterozygous variants in six additional patients for which parental information is not available." (PMID 35013161, 2022).
melanoma (1 paper, 2017). A malignant, usually aggressive tumor composed of atypical, neoplastic melanocytes. "Of note, the RBM5 promoter was identified as a “Signature of accelerated somatic evolution” in melanomas, with mutations in this region correlating with significantly lower survival rates and a higher incidence of metastasis." (PMID 28662214, 2017). "Therefore, altered RBM5 levels in melanoma may result in decreased translational regulation of RBM10, and thus the pro-transformation characteristics associated with RBM10 in melanomas, and here in our RBM5-null system." (PMID 28662214, 2017).
myeloid leukemia (1 paper, 2024). A clonal proliferation of myeloid cells and their precursors in the bone marrow, peripheral blood, and spleen. "These functional and molecular mechanisms further support RBM5 as a promising therapeutic target for myeloid leukemia treatment." (PMID 38216972, 2024). "Our functional experiments in vitro and in vivo support the oncoprotein role of RBM5 in myeloid leukemia." (PMID 38216972, 2024).
osteoporosis (1 paper, 2023). A condition of reduced bone mass, with decreased cortical thickness and a decrease in the number and size of the trabeculae of cancellous bone (but normal chemical composition), resulting in increased fracture incidence. "The LASSO model indicated that RNA-binding motif protein 5 (RBM5) is associated with osteoporosis and is a potential drug target." (PMID 38031049, 2023). "This study found that RBM5 is overexpressed in osteoporosis patients." (PMID 38031049, 2023). "Currently, the relationship between RBM5 and osteoporosis has not been investigated." (PMID 38031049, 2023).
pancreatic ductal adenocarcinoma (1 paper, 2013). An infiltrating adenocarcinoma that arises from the epithelial cells of the pancreas. "In the present study, we investigated the expression of RBM5 and KRAS at mRNA and protein levels and their associations with clinicopathological features in pancreatic ductal adenocarcinoma." (PMID 23425895, 2013). "The results indicate that the expression of the RBM5 protein is reversely correlated with the expression of the KRAS protein in pancreatic ductal adenocarcinomas (R=−0.892, P<0.01)." (PMID 23425895, 2013). "To assess the expression of RBM5 mRNA and protein in pancreatic ductal adenocarcinoma, we performed quantitative RT-PCR and western blot analysis on 45 pairs of cancerous vs. peritumoral tissues." (PMID 23425895, 2013). "This study aimed to detect RBM5 and KRAS expression in pancreatic ductal adenocarcinoma and their association with clinicopathological features." (PMID 23425895, 2013). "Our results revealed that the expression of RBM5 mRNA and protein is significantly decreased in pancreatic ductal adenocarcinoma in comparison to peritumoral tissues (P<0.05)." (PMID 23425895, 2013). "Collectively, expression of RBM5 and KRAS in pancreatic ductal adenocarcinomas is significantly decreased and increased, respectively, compared to non-tumor tissues." (PMID 23425895, 2013). "By Spearman’s rank test, we analyzed the correlation between protein expression of RBM5 and KRAS in 45 pancreatic ductal adenocarcinomas." (PMID 23425895, 2013).
R6/ (1 paper, 2023). "We demonstrated this by applying brain-pCLAP to the R6/2 HD mouse model and found that the RNA-binding ability of the alternative splicing factor RBM5 is altered." (PMID 37468457, 2023).